PNRC2 (proline rich nuclear receptor coactivator 2)
Description:
Involved in nonsense-mediated mRNA decay (NMD) by acting as a bridge between the mRNA decapping complex and the NMD machinery. May act by targeting the NMD machinery to the P-body and recruiting the decapping machinery to aberrant mRNAs. Required for UPF1/RENT1 localization to the P-body. Plays a role in glucocorticoid receptor-mediated mRNA degradation by interacting with the glucocorticoid receptor NR3C1 in a ligand-dependent manner when it is bound to the 5' UTR of target mRNAs and recruiting the RNA helicase UPF1 and the mRNA-decapping enzyme DCP1A, leading to RNA decay. Also acts as a nuclear receptor coactivator. May play a role in controlling the energy balance between energy storage and energy expenditure (By similarity).
Tractability: Small molecule: a structure with a bound ligand is known. PROTAC: ubiquitination databases record sites on it.
Gene: Protein-coding gene on chromosome 1 (23,956,839 to 23,963,776, forward strand). Ensembl gene ENSG00000189266.
Subcellular location: Nucleus; Cytoplasm, P-body
Subcellular location (Human Protein Atlas): Nucleoplasm; Golgi apparatus
Pathways (Reactome):
Metabolism of RNA: Nonsense Mediated Decay (NMD) enhanced by the Exon Junction Complex (EJC)
Gene Ontology:
Molecular function: protein binding
Biological process: nuclear-transcribed mRNA catabolic process, nonsense-mediated decay; deadenylation-independent decapping of nuclear-transcribed mRNA; nuclear-transcribed mRNA catabolic process
Cellular component: nucleoplasm; nucleus; P-body; cytosol
Genetic constraint (gnomAD): Loss-of-function variants: 1 observed, 10.52 expected, observed/expected ratio (o/e) 0.095, 90% interval 0.033 to 0.45. The upper end of that interval is the gene's LOEUF score, 0.45, which puts it in group 2 of 6, group 1 being the genes least tolerant of losing a copy. Missense variants: 103 observed, 125.58 expected, observed/expected ratio (o/e) 0.82, 90% interval 0.7 to 0.97. Synonymous variants: 36 observed, 42.57 expected, observed/expected ratio (o/e) 0.85, 90% interval 0.65 to 1.12.
Homologues: Orthologues: macaque PNRC2 (98% identical), pig PNRC2 (96% identical), dog PNRC2 (94% identical), rabbit PNRC2 (94% identical), guinea pig PNRC2 (93% identical), mouse Pnrc2 (83% identical), rat Pnrc2 (83% identical), tropical clawed frog pnrc2 (57% identical), zebrafish pnrc2 (48% identical), Drosophila melanogaster aqz (24% identical). Paralogues in human: PNRC1 (38% identical).
Diseases named in the same sentence as PNRC2 in open-access papers:
PNRC2 is named in the same sentence as 9 diseases in open-access papers, as found by Europe PMC text mining. Sharing a sentence is not in itself a finding about the gene and the disease. The quoted sentences say what the papers report.
colorectal cancer (2 papers, 2021). A primary or metastatic malignant neoplasm that affects the colon or rectum. "In colorectal cancer, PNRC2 is expressed at low levels and PNRC2 upregulated can inhibit cell proliferation, migration, invasion, and EMT." (PMID 34781983, 2021). "Interestingly, overexpression of OTUD6B-AS1 inhibits cell proliferation, migration, invasion, and promotes cell apoptosis in colorectal cancer by sponging miR-21-5p and regulating PNRC2." (PMID 34440306, 2021).
renal cell carcinoma (2 papers, 2020 to 2021). "PNRC2 encodes a coactivator which interacts with nuclear receptors using a proline-rich sequence, and it may be targeted by mir-23a-3p to further promote the progression of renal cell carcinoma." (PMID 33634092, 2020).
acute monocytic leukemia (1 paper, 2016). Acute monoblastic leukemia (AML-M5), is one of the most common subtypes of acute myeloid leukemia (AML) that is either comprised of more than 80% of monoblasts (AML-M5a) or 30-80% monoblasts with (pro)monocytic differentiation (AML-M5b). "Indeed, our previous data showed that down-regulation of GMD factors UPF1, PNRC2, or GR promotes the chemotaxis of human acute monocytic leukemia cell lines (THP-1 cells) by up-regulating CCL2 mRNA and CCL2 protein." (PMID 27798850, 2016).
breast carcinoma (1 paper, 2021). "PNRC2, belonging to the PNRC family, was first found in breast cancer." (PMID 34781983, 2021).
meningioma (1 paper, 2023). A generally slow growing tumor attached to the dura mater. "In the study, miR-3605-5p, miR-664b-5p, PNRC2, BTBD8, SLFN13, DGKD, NSD2, EXTL2, and BVES were closely corrected with the malignant progression of meningioma." (PMID 37024523, 2023).
tumor (2 papers, 2017 to 2021). "The second most down-regulated gene was neuritin 1 (NRN1), which has been proposed as hypoxic marker and potential marker for tumor angiogenesis, followed by the proline-rich nuclear receptor coactivator 2 (PNRC2), syntaxin 19, and early growth response 1 (EGR1)." (PMID 28402269, 2017).
cancer (1 paper, 2020). A tumor composed of atypical neoplastic, often pleomorphic cells that invade other tissues. "GTF2IRD2B and PNRC2 appear to carry hotspot mutations unique to Mongolian HCC; their mutation frequency is significantly higher than that observed in any other cancer type, as indicated by the asterisks." (PMID 32873799, 2020).
PNRC2 also shares sentences with these, for which no sentence is quoted: diabetes (1 paper); glioma (1).